ERBB3 (erb-b2 receptor tyrosine kinase 3)
Diseases named in the same sentence as ERBB3 in open-access papers (continued):
Sharing a sentence is not in itself a finding about the gene and the disease.
thyroid tumor (1 paper, 2023). A benign or malignant neoplasm affecting the thyroid gland. "In the GSE60542 cohort, our ROC analysis demonstrated that ERBB3 exhibits excellent discriminatory power for thyroid tumors (AUC=0.89)." (PMID 38144565, 2023). "We noted a significant upregulation of ERBB3 expression in thyroid tumors in both the validation set and TCGA-THCA cohort." (PMID 38144565, 2023). "Furthermore, the immunohistochemical analysis revealed a significant elevation in protein expression levels of ERBB3 in thyroid tumors compared to normal thyroid tissue." (PMID 38144565, 2023).
Tinnitus (1 paper, 2023). Tinnitus is an auditory perception that can be described as the experience of sound, in the ear or in the head, in the absence of external acoustic stimulation. "We report four CNVs in patients with MD and severe tinnitus: three rare deletions in the ERBB3 gene, and a large duplication involving AP4M1, COPS6, MCM7, and TAF6." (PMID 38254912, 2023). "Nevertheless, in the gnomAD dataset, four deletions were found overlapping one or more regions of the candidate SVs in ERBB3 for the individuals with severe tinnitus." (PMID 38254912, 2023). "We report the first CNVs observed in patients with MD and severe tinnitus in several unrelated patients: three deletions in the ERBB3 gene and a large duplication involving multiple genes." (PMID 38254912, 2023). "The SVs NC_000012.12:g.56100029_56100167del, NC_000012.12:g.56100244_56101058del, and NC_000012.12:g.56101363_56101526del found in the gnomAD database cover almost the same region as the three candidate deletions found in ERBB3 from the individuals with severe tinnitus." (PMID 38254912, 2023).
Tremor (1 paper, 2018). An unintentional, oscillating to-and-fro muscle movement about a joint axis. "Once again, we found that anti-NRG1, but not anti-ErbB3/anti-ErbB4 combination treatment caused tremor and a decrease in rearings." (PMID 29844389, 2018). "Moreover, treatment with a combination of both anti-ErbB3 and anti-ErbB4 inhibitory antibodies did not result in tremor or sensorimotor gating deficits, further supporting a receptor-independent mechanism of the anti-NRG1 phenotypes." (PMID 29844389, 2018).
xerostomia (1 paper, 2021). Dryness of the mouth resulting from reduced salivary secretion. "Interestingly, we find that BRCA2 and ERBB3 combination appeared to exhibit an additive effect on total rtAEs with a twofold increase or more in early dysphagia, early xerostomia and late dysphagia, compared to ERBB3 alteration alone." (PMID 34001187, 2021). "Interestingly, patients who exhibited alterations in both BRCA2 and ERBB3 experienced a twofold or greater increase in early dysphagia, early xerostomia and late dysphagia compared to ERBB3 alteration alone." (PMID 34001187, 2021). "Genetic alterations in BRCA2, ERBB3, NOTCH1 and CCND1 were all associated with higher mean grade of toxicity with BRCA2 alteration implicated in all toxicity parameters evaluated including mucositis, early dysphagia, xerostomia and to a lesser extent, late dysphagia." (PMID 34001187, 2021).
tumor (875 papers, 1998 to 2026). "Activated ERBB2/ERBB3 mutations have been reported to promote tumor cell proliferation and migration, as well as increase PD-L1 expression to induce immune evasion, and are associated with worse patient survival." (PMID 40116917, 2025). "ERBB3 expression has been associated with aggressive tumor features, including lymph node metastasis, and correlates with significantly worse overall survival outcomes." (PMID 40846695, 2025). "The study, further, utilizes CIBERSORTx to analyze the association between ERBB3 isoforms and immune cell profiles in the tumor microenvironment." (PMID 38276060, 2024). "We performed second-generation sequencing of her tumor sample and identified a simultaneous G284R mutation and amplification in ERBB3." (PMID 37681031, 2023). "NGS using the patient’s tumor tissue sample was tested and identified the ERBB3 G284R mutation and amplification as major oncogenic molecular alteration." (PMID 37681031, 2023). "Examples of receptors overexpressed in SCLCs included ERBB3 (tumor ligands NRG1, NRG2) and GDNF receptor 1 encoding GFRA1 (ligand NCAM1)." (PMID 36271074, 2022). "These in vivo data demonstrated that the adenovirus-mediated silencing of ErbB3 caused efficient tumor growth suppression, resulting in increased survival of the animals." (PMID 35806132, 2022). "Insights from ERBB3's role during mammary development can have implications for our understanding of tumor biology in the context of ERBB2/ERBB3 oncogenic mutation and/or amplification." (PMID 36618440, 2021). "In the present study, we observed that low values of serum ERBB3 resulted associated with longer OS; interestingly, the association remained significant even after adjustment for patients’ age, liver function, and tumor stage (HR = 2.24, p = 0.017)." (PMID 33799723, 2021). "Backgrounds with increased polyp number with loss of ERBB3 showed an increase in cell proliferation even in non-tumor epithelia, while backgrounds showing reduced polyp number with loss of ERBB3 showed reduced cellular proliferation." (PMID 34843459, 2021). "CSPG5 is only expressed in the human brain, and a study showed that it has a new function that binds to ERBB3 tyrosine kinase, and the ERBB3 somatic mutation is a potential tumour driver." (PMID 33962640, 2021). "Second, the single-domain antibodies present a perfect template for the production of antibody–drug conjugates, those efficiency against an ErbB3-expressing tumor was demonstrated with a conventional antibody linked to a plant toxin saporin." (PMID 34572289, 2021). "A novel ERBB3 TMD mutation I649R was found in tumor tissue of three patients with ERBB2 V659D (P03, P13, and P17)." (PMID 32478891, 2020). "Due to ErbB2 and ErbB3 mutations at a frequency of 7–8% in GBC, ErbB2/ErbB3 mutation inducing PD-L1 overexpression can mediate immune escape of tumor cells via PI3K/AKT pathway in vitro." (PMID 32333246, 2020). "The results demonstrated that acquired ERBB2/ERBB3 mutations by tumor cells are essential to induce checkpoint PD-L1, rendering tumor cells evasive from cytotoxic T cell immunity against tumor." (PMID 33028805, 2020). "Receptor tyrosine-protein kinases ErbB2 (proto-oncogen) and ErbB3 (a dimer partner of ErbB2) were implicated in tumor growth, proliferation, and chemotherapeutic resistance." (PMID 33383894, 2020). "In one of the cases, an ERBB3 E928G mutation was present in the mastopathy as well as in the tumor tissue, with the variant allele frequency in the mastopathy being <0.1%." (PMID 31396514, 2019). "In one of the cases, an ERBB3 E928G mutation was present in the mastopathy as well as in the tumor tissue, although the variant allele frequency in the mastopathy was <0.1%." (PMID 31396514, 2019). "Multi-cytokine responses were inter alia directed against known tumor antigens such as cyclin D1 but also against a (predicted) mutation contained in ERBB3." (PMID 31803175, 2019).
tumor (continued). "In the last years, the deregulation of ErbB2/ErbB3 machinery is also emerging as an oncogenic trait of lung adenocarcinoma with mucinous pattern, a tumor subtype that is otherwise associated with KRAS mutations." (PMID 29515761, 2018). "The fact that DFT1 expresses tumour associated antigens (TAA’s) such as ERBB3 invites the application of monoclonal antibodies and therapeutic cancer vaccines as prospective treatments." (PMID 28591206, 2017). "Evidence suggests that elevated expression of ERBB3 plays an important role in the progression of several tumor forms indicating that increased ERBB3 levels are linked to the regulation of cell proliferation and potentially apoptotic cell death." (PMID 28212332, 2017). "ERBB2 and ERBB3 overexpression, cooperation in neoplastic transformation and loss of ERBB3 preventing the progressive transformation of ERBB2-over expressing tumours reinforces ERBB3’s pivotal role in ERBB signalling." (PMID 28591206, 2017). "This indicated that besides the KRAS G12D driver mutation that was present in the respective primary tumor and CTCs, there was also a tumor subclone with an ERBB3 mutation that was shed into the circulating blood." (PMID 28978093, 2017). "In support of this, shRNA knockdown of ERBB3 in vivo in cells with endogenous ERBB3 mutations moderately but statistically significantly delayed tumor growth." (PMID 29371993, 2017). "Other studies have clarified that miR-148a is significantly decreased in breast cancer cells associated with tumor angiogenesis, function as tumor suppressors to inhibit angiogenesis by targeting ERBB3." (PMID 28464803, 2017). "More importantly, for the first time, we found that the anti-tumor mechanism of PF was highly associated with the inhibition of ErbB3 phosphorylation." (PMID 27609096, 2016). "In tumor cells, NN drives a stable, homotypic association of ErbB3, which traps ErbB3, keeping it away from undesirable oncogenic signaling with ErbB2." (PMID 27596216, 2016). "ErbB3 protein expression was also higher in HBV-associated tumor tissues than in their adjacent normal tissues." (PMID 26595522, 2016). "Strikingly, the only receptor whose activation was observed to increase upon Trop2 loss was ErbB3, a member of the ErbB family implicated in several aspects of aggressive tumor behavior." (PMID 25238142, 2014). "The authors conclude that downregulation of KRT19 is highly associated with tumor progression in NB and metastasis in localized primary NB and that low expression of ERBB3 is also associated with progression of NB." (PMID 23135478, 2013). "Ablation of endogenous Erbb3 in mammary epithelial cells caused a decrease in ERBB2 induced tumor incidence from 93.3% to 6.7%." (PMID 23593223, 2013). "Considering the role of the oncogenic ErbB2-ErbB3 unit, it will be interesting to determine if activating ErbB3 mutations are uncovered in tumours that have low ErbB2 expression." (PMID 23202898, 2012). "High expression of ErbB3 has been shown to have a positive association with tumour size, recurrence, metastasis and significantly reduced patient survival." (PMID 21396094, 2011). "To study cross-species functional interactions between the rat c-neu/ErbB2 transgene and mouse ErbB3, we evaluated tumor and tissue expression in vivo, ligand-associated interactions, and signaling in vitro." (PMID 16168116, 2005). "Most tumor-derived cell lines express significant mouse ErbB3-encoded protein, in addition to high levels of the rat c-neu/ErbB2 transgene." (PMID 16168116, 2005). "Furthermore, reduced ErbB3 levels were associated with clinically aggressive features, including positive lymph node status, larger tumor size, triple-negative subtype, and basal-like phenotype." (PMID 41348103, 2026).
tumor (continued). "Our findings presented in this report suggest that overexpression of DARPP-32 isoforms in EGFR-mutated NSCLC promotes EGFR:ERBB3 “bypass signaling” that enables tumor cells to evade EGFR TKI monotherapy-induced apoptosis by potentiating oncogenic AKT and ERK signaling." (PMID 34675407, 2022). "Poor-quality tumour DNA precluded assessment of ERBB3 mutation(s) in our family, noting that somatic mutations were not identified in the single family with the germline ERBB2 mutation and NSCLC and inconsistently in individuals and families with EGFR/ERBB1 mutations." (PMID 34274969, 2021). "Despite differences in tumor number, the size of ERBB3-deficient intestinal polyps was reduced on all three genetic backgrounds, albeit only significantly across all regions of the intestinal tract in the B6;129 mixed background that also showed a significant decrease in polyp number." (PMID 34843459, 2021). "Based on the known background sensitivity of EGFR, deletion of both Egfr and Erbb3 on a C57BL/6J background showed a dramatic decrease in polyp number indicating the tumor increase with loss of ERBB3 on the C57BL/6J background was at least partially mediated by EGFR." (PMID 34843459, 2021). "The quality and quantity of available tumour samples limited the ability to perform additional functional studies of these other variants (as well as limiting assessment for additional somatic mutations in ERBB3 )." (PMID 34274969, 2021). "Moreover, the overexpression of ERBB1 and ERBB3 is linked with more aggressive tumor with high proliferation index, intrahepatic metastasis, de-differentiation, and tumor size." (PMID 31450841, 2019). "We also noted reduced expression of other cancer-associated proteins in iSCs within the endoneurial compartment compared to those within the epineurial compartment, including ErbB3 and N-cadherin, both associated with dysregulated growth factor signaling in tumor growth." (PMID 30364248, 2018). "Many cancer-related genes were rearranged, such as the region containing the tumour suppressor NF2 and a copy gain for ERBB3, a member of the epidermal growth factor receptor family of receptor tyrosine kinases implicated in proliferation and invasion of tumours in humans." (PMID 28821767, 2017). "Besides, SNP rs3202538 (G/T) in ErbB3 3′-UTR was involved in the occurrence of GC by acting as tumor risk factors." (PMID 28924391, 2017). "Interestingly, when crossed to ApcMin mice, ErbB3 loss almost completely prevented colonic tumorigenesis, underscoring the important role of ErbB3 signaling in tumor establishment and progression." (PMID 27447549, 2016). "In addition, positive correlation between HBx and ErbB3 protein expressions in these HBV-associated tumor tissues was also obtained." (PMID 26595522, 2016). "We therefore hypothesized that ERBB2 and ERBB3 activating mutations might be over-represented in ILC harboring atypical features such as high tumor grade or ERBB2 amplification." (PMID 27602491, 2016). "Moreover, the mutation frequency in the corresponding normal sample was comparable to that in the tumor sample and patient P83 was affected by a germline mutation in the TK-domain of ERBB3 but a somatic mutation in the ligand-binding domain of IGF1R." (PMID 27246973, 2016). "Moreover, NRG-1β, the ligand for ErbB-3, is released by tumor-associated stromal cells and has been suggested to promote CRC progression as well as compensate for loss of EGF/EGFR signaling." (PMID 26160848, 2015). "Activation of RTK signaling caused by HRG-associated heterodimerization of ErbB3 and ErbB2 may be a critical step in tumor progression." (PMID 23937725, 2013). "Downregulation of ERBB3 in NB might suggest similar kinase switching during the EMT followed by tumor survival with the loss of EGF dependency." (PMID 23135478, 2013). "Cytoplasmic ERBB3 was associated with high tumour grade (P=0.01) and with ERBB2 positivity." (PMID 21364580, 2011).
tumor (continued). "ErbB3 expression was also similar between the two groups, suggesting that p190B deficiency does not inhibit Neu-induced tumorigenesis by altering the epidermal growth factor receptor signaling axis that promotes tumor formation in this model." (PMID 19703301, 2009). "We hypothesised that co-targeting the preferred ErbB2/ErbB3 heterodimer with a bispecific single-chain Fv (bs-scFv) antibody would promote increased targeting selectivity over antibodies specific for a single tumour-associated antigen (TAA)." (PMID 18841159, 2008). "Given that these PI3K and MAPK signaling pathways are upregulated during resistance, we hypothesized that overexpression of DARPP-32 proteins in EGFR-mutated NSCLC may promote EGFR:ERBB3 “bypass signaling” that enables tumor cells to evade EGFR TKI monotherapy." (PMID 34675407, 2022). "Combinatorial approaches including scRNA-seq, functional genomics, and mechanistic studies revealed ERBB3 as the critical paracrine factor mediating oligodendrocyte-tumor crosstalk." (PMID 42003929, 2026). "Mechanistically, oligodendrocyte-secreted ERBB3 acts as a copper chaperone that competitively mobilizes extracellular copper ions through high-affinity binding to SLC31A1 on tumor cells, thereby promoting intracellular copper accumulation." (PMID 42003929, 2026). "Human epidermal growth factor receptor 3 (HER3/ErbB3) is a tyrosine kinase receptor with oncogenic properties, including promotion of tumor growth, invasion, and resistance to therapy." (PMID 40461013, 2025). "This study establishes a basis for combining ERBB3 inhibition with ferroptosis inducers like GPX4 inhibitors to achieve increased anti-tumor effects." (PMID 40846695, 2025). "Our findings provide important insight into unmet therapeutic needs for patients with cancers harboring ERBB2/ERBB3 alterations, which is essential for a new paradigm of pan-tumor HER2-targeted therapy." (PMID 40178042, 2025). "The low prevalence of ERBB2 and ERBB3 activating alterations across a variety of tumor types supports a tumor agnostic approach to investigations." (PMID 40178042, 2025). "The HER3 receptor (ERBB3) has emerged as an important player in cancer progression, contributing to aggressive tumor behavior and poor prognosis." (PMID 40846695, 2025). "The ErbB receptor family (EGFR, HER2, ErbB3, ErbB4) is expressed in lactotroph cells, promoting prolactin secretion, and inhibiting these receptors can lead to tumor regression." (PMID 41013821, 2025). "Estrogen also plays a role in the PI3K/AKT pathway, which mediates the ERBB2/ERBB3 oncogenic signalling pathway that promotes tumour development and progression." (PMID 38974022, 2024). "We report two cases of mutations with low evidence for actionability based on the OncoKB database (BRCA2 S497L and ERBB3 G284R), but for which our local molecular tumor board suggested therapeutic options that led to sustained tumor responses." (PMID 38664720, 2024). "Further research should also delve into the interactions of ERBB3 isoforms with other molecular pathways in the tumor microenvironment, potentially unveiling new therapeutic targets and deepening our understanding of RCC pathophysiology." (PMID 38276060, 2024). "The antitumor potential of this formulation and the induced PAbs was demonstrated in vivo and in vitro in an ErbB3-overexpressing 3LL-D122-derived tumor model." (PMID 39479017, 2024). "The histogenesis of this tumor, its appropriate classification and the potential benefit of targeting the underlying ERBB2/ ERBB3 tyrosine kinase mutation remain to be verified in the future." (PMID 39196362, 2024). "Taken together, these observations suggest that all the ERBB3 variants can be targeted in ERBB3/ERBB2 heterodimeric complexes with anti-ERBB antibodies or TKI’s but that the sensitivity may depend on the availability of activating ligands in the tumor microenvironment." (PMID 38806620, 2024).